RNU6-1231P (RNA, U6 small nuclear 1231, pseudogene)
Gene: Small nuclear RNA gene on chromosome 10 (102,803,929 to 102,804,031, forward strand). Ensembl gene ENSG00000252994.
Homologues: Orthologues: chimpanzee U6 (99% identical), dog U6 (85% identical), mouse Gm24204 (84% identical). Paralogues in human: RNU6-1243P (86% identical), RNU6-379P (84% identical), RNU6-43P (84% identical), RNU6-944P (84% identical), RNU6-1251P (83% identical), RNU6-255P (83% identical), RNU6-879P (83% identical), RNU6-1060P (83% identical), RNU6-1094P (83% identical), RNU6-1175P (83% identical), RNU6-1327P (83% identical), RNU6-1331P (83% identical), and 1282 more.